MIR4521 (microRNA 4521)
Synonyms: hsa-mir-4521; mir-4521
Gene: MicroRNA gene on chromosome 17 (8,186,945 to 8,187,004, forward strand). Ensembl gene ENSG00000283160.
Diseases named in the same sentence as MIR4521 in open-access papers:
MIR4521 is named in the same sentence as 3 diseases in open-access papers, as found by Europe PMC text mining. Sharing a sentence is not in itself a finding about the gene and the disease. The quoted sentences say what the papers report.
diabetes (1 paper, 2024). "The present study elucidated the potential VED-associated mechanisms in diabetes, with a specific focus on the complicated mutual effects between circHMGCS1 and MIR4521." (PMID 39235443, 2024). "Conversely, restoring MIR4521 expression effectively alleviated VED progression, highlighting the critical role of MIR4521 in counteracting circHMGCS1-mediated promotion of diabetes-induced VED." (PMID 39235443, 2024). "AAV9-mediated circHMGCS1 overexpression in endothelial cells dampened MIR4521 expression and accelerated diabetes-induced VED." (PMID 39235443, 2024). "In this study, aberrant expression levels of circHMGCS1 and MIR4521 were observed in diabetes-induced human umbilical vein endothelial cell dysfunction." (PMID 39235443, 2024). "AAV9-mediated circHMGCS1 overexpression attenuates the protective effect of MIR4521 against diabetes-induced VED." (PMID 39235443, 2024). "We demonstrated that the upregulation of circHMGCS1 and downregulation of MIR4521 significantly promoted diabetes-induced VED." (PMID 39235443, 2024). "Our functional studies revealed that MIR4521 mimics attenuated VED development in diabetes, whereas its inhibition exacerbated VED progression." (PMID 39235443, 2024). "ARG1 is inseparable from circHMGCS1 and MIR4521 regulating diabetes-induced VED." (PMID 39235443, 2024). "Our findings suggest that targeted inhibition of circHMGCS1 or the overexpression of MIR4521 could serve as effective strategies in mitigating diabetes-induced VED." (PMID 39235443, 2024). "Therefore, ARG1 may serve as a promising VED biomarker, and circHMGCS1 and MIR4521 play a key role in regulating diabetes-induced VED by ARG1." (PMID 39235443, 2024). "Moreover, the absence of MIR4521 aggravated diabetes-induced VED, whereas exogenous circHMGCS1 addition did not affect VED development." (PMID 39235443, 2024). "In the absence of MIR4521, circHMGCS1 cannot regulate ARG1 expression, whereas exogenous MIR4521 intervention inhibits the diabetes-induced increase in ARG1 expression in vivo, and this effect is counteracted by circHMGCS1 overexpression." (PMID 39235443, 2024).
endothelial dysfunction (1 paper, 2024). In vascular diseases, endothelial dysfunction is a systemic pathological state of the endothelium (the inner lining of blood vessels) and can be broadly defined as an imbalance between vasodilating and vasoconstricting substances produced by (or acting on) the endothelium. "circHMGCS1 regulates PAHG-induced endothelial dysfunction by targeting and sponging MIR4521." (PMID 39235443, 2024).
MIR4521 also shares sentences with these, for which no sentence is quoted: cardiovascular diseases (1 paper).